TMC3 (transmembrane channel like 3)
Description:
Probable component of an ion channel (Probable). Molecular function hasn't been characterized yet (Probable).
Tractability: Antibody: UniProt predicts a signal peptide or a membrane-spanning region; its Gene Ontology location is reachable by antibodies, with medium confidence.
Gene: Protein-coding gene on chromosome 15 (81,331,088 to 81,374,213, reverse strand). Ensembl gene ENSG00000188869.
Subcellular location: Membrane
Subcellular location (Human Protein Atlas): Cytosol
Gene Ontology:
Molecular function: mechanosensitive monoatomic ion channel activity
Biological process: monoatomic ion transmembrane transport
Cellular component: cytosol; plasma membrane; membrane
Genetic constraint (gnomAD): Loss-of-function variants: 83 observed, 96.4 expected, observed/expected ratio (o/e) 0.86, 90% interval 0.72 to 1.03. The upper end of that interval is the gene's LOEUF score, 1.03, which puts it in group 4 of 6, group 1 being the genes least tolerant of losing a copy. Missense variants: 1,262 observed, 1,322.4 expected, observed/expected ratio (o/e) 0.95, 90% interval 0.91 to 1. Synonymous variants: 476 observed, 502.78 expected, observed/expected ratio (o/e) 0.95, 90% interval 0.88 to 1.02.
Homologues: Orthologues: chimpanzee TMC3 (99% identical), macaque TMC3 (97% identical), pig TMC3 (82% identical), dog TMC3 (82% identical), mouse Tmc3 (82% identical), rabbit TMC3 (81% identical), rat Tmc3 (81% identical), guinea pig TMC3 (79% identical), tropical clawed frog TMC3 (62% identical), Drosophila melanogaster Tmc (33% identical), zebrafish si:dkey-15b23.3 (24% identical). Paralogues in human: TMC2 (30% identical), TMC1 (26% identical), TMC7 (17% identical), TMC4 (15% identical), TMC8 (15% identical), TMC6 (14% identical), TMC5 (14% identical).
Diseases named in the same sentence as TMC3 in open-access papers:
TMC3 is named in the same sentence as 2 diseases in open-access papers, as found by Europe PMC text mining. Sharing a sentence is not in itself a finding about the gene and the disease. The quoted sentences say what the papers report.
parathyroid adenoma (1 paper, 2021). "Immunohistochemistry showed that the expression of TMC3 was higher in parathyroid adenoma than that in normal parathyroid tissue." (PMID 34899684, 2021). "Moreover, immunochemistry data further validated the higher expression level of TMC3 in parathyroid adenoma compared with parathyroid glands." (PMID 34899684, 2021). "The expression of TMC3 could be a specific classifier to distinguish the parathyroid adenoma samples and the normal parathyroid tissue." (PMID 34899684, 2021). "Surprisingly, we discover that TMC3 was specifically expressed in parathyroid tissue and could distinguish the parathyroid adenoma (higher TMC3 levels) and normal parathyroid glands (lower TMC3 levels)." (PMID 34899684, 2021).
cancer (1 paper, 2019). A tumor composed of atypical neoplastic, often pleomorphic cells that invade other tissues. "Interestingly, three out of the five non-synonymous mutated genes, Transmembrane Channel Like 3 (TMC3), Olfactory Receptor Family 6 Subfamily K Member 6 (OR6K6), and Unc-5 Family C-Terminal Like (UNC5CL), have been reported on in regard to an involvement with various cancer types." (PMID 31842489, 2019).